SIRT1 (sirtuin 1)
Diseases named in the same sentence as SIRT1 in open-access papers (continued):
Sharing a sentence is not in itself a finding about the gene and the disease.
Obesity (continued). "From these findings, one could speculate that during obesity, these two upregulated miRNAs could influence the endothelial function through decreasing SIRT1 and inducing premature senescence pathways." (PMID 32907629, 2020). "Thus, given the lowest amount of FM, the patients with AN showed the highest plasma levels of SIRT1 and adiponectin and the lowest concentration of leptin, while the opposite was found in the group of patients with obesity." (PMID 33202604, 2020). "Interestingly, the levels of SIRT1 decrease in mice upon diet-induced obesity, as well as during ageing." (PMID 32358737, 2020). "In view of the beneficial effects of both adiponectin and SIRT1 on metabolic health, their reduction in concentration in obesity could be either a mirror or a contributing factor to the deleterious effects of excess adipose tissue." (PMID 33202604, 2020). "Silent mating-type information regulation 2 homolog 1 (SIRT1, sirtuin 1), a nicotinamide adenine dinucleotide (NAD+)-dependent deacetylase, has been implicated in a variety of physiological processes, including senescence, obesity, and inflammation." (PMID 33316776, 2020). "Interestingly, SIRT1 has been found to be reduced during obesity, thereby leading to endothelial dysfunction." (PMID 32907629, 2020). "Due to the critical roles of AMPK and SIRT1 in muscle mitochondrial changes induced by obesity, they might be potential targets to prevent and/or treat obesity and obesity-related metabolic dysfunction." (PMID 31744213, 2019). "The Sir2/Sirt1 gene overexpression delays cell aging and reduces obesity and oxidative stress." (PMID 31503544, 2019). "Given this close association between AMPK/SIRT1 activation and muscle mitochondrial biogenesis and function, AMPK/SIRT1 could be a critical target for the prevention/treatment of obesity and its related metabolic effects." (PMID 31744213, 2019). "Recently, SIRTs, specifically SIRT1, have become a focus of intense anti-obesity research." (PMID 29541908, 2019). "It suggests that vitamin D supplementation might improve obesity-increased intramyocellular fat deposition and its associated muscle mitochondrial changes, concurrently with an increase in AMPK/SIRT1 activity." (PMID 31744213, 2019). "There is a correlation between obesity and reduced Sirt1 levels." (PMID 31130916, 2019). "SIRT1 up-regulation is effective against obesity and insulin resistance in NAFLD rodents." (PMID 31500354, 2019). "Excess circulating fat, as seen in obesity, has been shown to decrease β-cell function, an effect that may involve decreased SIRT1 activity." (PMID 30890694, 2019). "SIRT1 levels are transcriptionally regulated by nutrient availability, and the expression of SIRT1 gene is inhibited by Carbohydrate response element binding protein (ChREBP) in obesity or diabetes." (PMID 31533364, 2019). "In this report, we have shown that UDCA reverses obesity-reduced SIRT1, PGC1α, and Tfam expression, that also increased mitochondria complex I, II, V mRNA expression in ob/ob mice, suggesting UDCA is a potential agent to promote mitochondrial biogenesis and improved mitochondrial function." (PMID 30884843, 2019). "Sirt1 proteins participate in regulating cell aging, diabetes, obesity, and oxidative stress." (PMID 31503544, 2019). "The effects of SIRT1 on integration of metabolism and inflammation may provide a therapeutic target for treatment of obesity-related diseases." (PMID 30988688, 2019).
Obesity (continued). "Adipogenesis derailment at this early age is suggested by decreased expression of adiponectin, the fat mass and obesity-associated gene, and the adiponectin receptor R1, coupled with a reduction of the brown fat biomarker PAT2 and the adipogenesis inhibitor SIRT1." (PMID 31554925, 2019). "We analyzed Sirt1 mRNA expression in the epididymal adipose tissue to determine whether the anti-obesity effect of GPE was due to a change in SIRT1 expression." (PMID 31618980, 2019). "Furthermore, Sirt1 decreases fat storage, increases lipolysis in adipose tissue and protects against obesity-induced inflammation." (PMID 31731817, 2019). "The role of NAD+ and SIRT1 deacetylation activation as an inflammation rheostat emerged when multiple studies reported that obesity and other chronic pro-inflammatory states are associated with reduced NAD+, NAMPT and SIRT1 levels in monocytes and other immune cells." (PMID 30216989, 2018). "The activation of SIRT1 by its activators (e.g. resveratrol) may protect against high-fat-induced obesity and insulin resistance." (PMID 29618822, 2018). "Resveratrol, a SIRT1 activator, protects against obesity and the development of insulin resistance." (PMID 30275871, 2018). "SIRT1 association to the Tac3 promoter decreased between late juvenile development and the completion of puberty, but neither obesity nor undernourishment altered this association." (PMID 30305620, 2018). "SIRT7 and SIRT1 promoters' methylation status are not closely associated with the upregulation or downregulation of their mRNA levels induced by obesity." (PMID 30559718, 2018). "Moreover, SIRT1 and SIRT6 have been implicated in obesity, insulin resistance, type 2 diabetes mellitus (T2DM), fatty liver disease and cardiovascular diseases." (PMID 30574122, 2018). "SIRT1 in the POMC neurons is required to protect against high calorie-induced obesity." (PMID 30532738, 2018). "This suggests that the antioxidant effect of verbascoside might be regulated through the increase in SIRT1 activity, leading to treatment of obesity and related metabolic disorders through AMPK activation." (PMID 30200432, 2018). "SIRT1 expression has been found to generally decrease with age and obesity." (PMID 30513672, 2018). "POMC neurons-specific SIRT1 knockout mice are vulnerable to diet-induced obesity." (PMID 30559718, 2018). "The polyphenols, especially resveratrol, are activators of Sirt1 and they can improve obesity." (PMID 30263038, 2018). "In addition, overexpression of SIRT1 in obesity which was formed by high-fat diet protects lipid-induced inflammation and hepatic steatosis while providing better glucose tolerance." (PMID 30374331, 2018). "Decreased AT SIRT1 expression in obesity had also been reported in other human studies." (PMID 29417372, 2018). "In addition to the obesity, SIRT1 has a role in the hepatic energy metabolism by modulating it nutritionally and hormonally." (PMID 30374331, 2018). "SIRT1 is also defensive against diabetes and obesity in the steroidogenic factor 1 neurons." (PMID 30559718, 2018). "The overexpression of SIRT1 in POMC neurons was able to rescue FoxO1 activation induced obesity." (PMID 30532738, 2018). "Given the close relationship between AMPK and SIRT1 activation and their effects on obesity and its-associated inflammation, AMPK/SIRT1 activity could be a target for prevention or treatment of obesity-associated endocrine and metabolic effects." (PMID 28353634, 2017). "In addition, we previously reported that miR-146b promotes adipogenesis and obesity by downregulating SIRT1." (PMID 28445161, 2017). "Recently, another component of the Mediterranean diet, resveratrol, has been shown to modulate positively gut microbiota enhancing glucose tolerance in a mice model of obesity and also through a duodenal Sirt-1 pathway into the hypothalamus enhancing hypothalamic insulin-resistance." (PMID 28335507, 2017).
Obesity (continued). "Thus, AMPK and SIRT1 activation have been proposed as key regulators to prevent obesity and obesity-related metabolic dysfunction." (PMID 28353634, 2017). "Recently, we observed that FK866 significantly aggravated the high fat diet-induced obesity in mice, in which the NAMPT inhibition-induced obesity might be involved in suppression of Sirt1-SREBP1-FASN signaling pathway in adipose cells (unpublished data)." (PMID 28449683, 2017). "Many miRNAs have been reported to regulate SIRT1 under different circumstances; however, the mechanism by which miRNAs regulate SIRT1 during obesity-induced inflammation remains unclear." (PMID 29050301, 2017). "In obesity, there is a decrease in sirtuin 1 levels and activity." (PMID 29163354, 2017). "Furthermore, we investigated the potential mechanism by which miR-377 mediated regulation of SIRT1 expression in adipocyte inflammation and insulin-resistance during obesity." (PMID 29050301, 2017). "Therefore, activating SIRT1 pharmacologically should be beneficial in treating obesity and age-related diseases." (PMID 28445161, 2017). "What is interesting is this study did not point at two other SIRT1 SNPs: rs7069102 and rs1467586, both associated with obesity in Belgian and Dutch populations, respectively." (PMID 27104517, 2016). "We have further evidenced the presence of SIRT1 in DM, obesity, and DR." (PMID 27699170, 2016). "Previous studies have reported the detailed role of SIRT1-AMPKα axis in obesity." (PMID 27143989, 2016). "In particular, this study demonstrates that OLE exerts beneficial effects against obesity by overexpressing sirtuin 1 (SIRT-1), peroxisome proliferator-activated receptor alpha (PPARα), and peroxisome proliferator-activated receptor gamma (PPARγ), coactivator 1 alpha (Pgc-1α)." (PMID 27303302, 2016). "Therefore, these previous reports suggest the important role of SIRT1-AMPKα axis, or circle, in obesity." (PMID 27143989, 2016). "An additional parallel with Sirt1 is seen in our tissue-specific studies, where we show that sir2 function is necessary and sufficient in the fat body to maintain insulin signaling and suppress hyperglycemia and obesity, analogous to the role of Sirt1 in the liver and white adipose." (PMID 27058248, 2016). "Recently, Sirt1 has emerged as a novel therapeutic target in the fight against obesity." (PMID 27669202, 2016). "Supporting this concept is that SIRT-1 and 2 activation attenuates obesity-related inflammation." (PMID 27500833, 2016). "In rats with diet-induce obesity, brain SIRT1 inhibition increased POMC that leads to an increase in α-melanocyte-stimulating hormone (α-MSH), which could in turn increase thyroid releasing hormone and T3 levels." (PMID 25805970, 2015). "However, the actions of microglial SIRT1 in the context of obesity, induced by aging or by diet, remain elusive." (PMID 26236282, 2015). "Furthermore, Chau demonstrated that FGF21 was a potential function as a therapy for obesity by activating AMPK-sirtuin 1 (SIRT1)-PGC-1α pathway." (PMID 26703591, 2015). "Using a rat model of moderate obesity and insulin resistance and a cell model of hepatocyte steatosis, we report up-regulation of adiponectin, Sirt1/6, and downstream targets of Sirt1/6, and also, increases in both LKB1 and AMPK activities following RGZ treatment." (PMID 25133775, 2014). "Importantly, it has been described that obesity results in decreased SIRT1 levels, both in rodent and human adipose tissue." (PMID 24567900, 2014). "Thus, liver-specific deletion of SIRT1 had increased fatty liver disease and obesity induced inflammation, while SIRT1 over-expression showed protective effects against steatohepatitis and insulin resistance." (PMID 25195642, 2014). "Thus, we used SRT1720, the specific activator of SIRT1, to investigate its effect on the follicle development of the high-fat diet induced obesity mice." (PMID 25330910, 2014).
Obesity (continued). "The reason for this decrease might rely on the fact that obesity triggers the cleavage of SIRT1 through a caspase-1 dependent mechanism." (PMID 24567900, 2014). "Notably, resveratrol, a Sirt1 activator, protects against obesity and type 2 diabetes in mice fed with a high-fat diet." (PMID 24614171, 2014). "Obesity is associated with ageing and increased energy intake, while restriction of energy intake improves health and longevity in multiple organisms; the NAD+-dependent deacetylase sirtuin 1 (SIRT1) is implicated in this process." (PMID 24374551, 2014). "We next tested whether Sirt1 overexpression in POMC neurons or AgRP neurons protects mice from diet-induced obesity by feeding them an HFHS diet." (PMID 24374551, 2014). "In the current study we tested whether conditional Sirt1 overexpression in mouse POMC or AgRP neurons prevents age-associated weight gain and diet-induced obesity." (PMID 24374551, 2014). "However, Sirt1 deficiency in mice leads to hepatic steatosis and inflammation, and liver-specific Sirt1 knockout mice develop severe hepatic steatosis and late-onset obesity with impaired whole-body energy expenditure." (PMID 25133775, 2014). "We discuss here the role of Sirt1, and speculate on the possible involvement of Sirt1, in renal diseases in patients with diabetes and obesity." (PMID 25126552, 2014). "Resveratrol is known to exert pleiotropic effects on cells and Sirt1 activation is not the only effect via which resveratrol exerts its beneficial actions on obesity-associated pathological consequences." (PMID 23819014, 2013). "Accumulating evidence suggests that AMPK and Sirt1 act as intracellular energy sensors and regulate energy metabolism through a concert process, and thus are of great interest in recent years as molecular targets in obesity research." (PMID 23922935, 2013). "The anti-inflammatory property of AMPK and SIRT1 may contribute to their beneficial effects in antagonizing obesity-induced insulin resistance." (PMID 23183898, 2012). "Via this way, PARP-2 gene deletion induced SIRT1 levels in all tissues and cell models tested, subsequently promoting mitochondrial biogenesis, enhancing the ability to oxidize fat and preventing against the onset of diet-induced obesity." (PMID 21566260, 2011). "SIRT1 is one of the targets of resveratrol, a polyphenol that has been shown to increase lifespan and to protect animal models against high-calorie diet induced obesity and insulin resistance." (PMID 21483037, 2011). "Regulation of UCP2 by Sirt1 may also be an important axis that is dysregulated by excess fat to contribute to obesity induced diabetes." (PMID 21549004, 2011). "Thus, activation of SIRT1 maintains gut barrier function, which is compromised in obesity and through its regulation of gut inflammation controls colitis and colon cancer, which are also more prevalent in obese individuals." (PMID 22115311, 2011). "The deletion of either the PARP-1 or PARP-2 gene in mice enhances SIRT1 activity, which leads to a higher mitochondrial content, ability to oxidize fatty acids, ultimately culminating in the prevention against diet-induced obesity." (PMID 21566260, 2011). "For example, SIRT1 activation confers a therapeutic effect in type 2 diabetes, obesity and neurodegenerative diseases such as Alzheimer's and amyotrophic lateral sclerosis, whereas inhibition of mTOR is protective against cardiovascular and neurological diseases, diet-induced obesity and cancer." (PMID 20169165, 2010). "Given the role of Sirt1 in several peripheral tissues and hypothalamus, potential therapies centered on Sirt1 regulation might provide promising therapies in the treatment of metabolic diseases including obesity." (PMID 20020036, 2009). "This regulation of energy and metabolic homeostasis by SIRT1 has implications for understanding the consequences of selective nutrient adaptation and how it might impact lifespan or metabolic diseases such as obesity and diabetes." (PMID 21566744, 2008).
Obesity (continued). "However, whether the SIRT1 level in subcutaneous adipose tissue (SAT) matches with its circulating form in obesity is unknown." (PMID 42075052, 2026). "Given that SIRT1 is known to regulate insulin resistance in skeletal muscle the observed suppression of obesity may be partially related to increased energy consumption in skeletal muscle through the control of insulin resistance induced by increased SIRT1 expression." (PMID 40783584, 2025). "This suggests that activating or overexpressing SIRT1 may reduce obesity." (PMID 41304967, 2025). "However, current research has rarely explored the effects of HIIT exercise on hippocampal neuronal damage and cognitive function induced by obesity, particularly the improvement of hippocampal neuronal damage and CI in obese rats by regulating the SIRT1/PGC1α pathway." (PMID 41140914, 2025). "Therefore, estradiol could mitigate the effects of obesity on UAM damage by enhancing SIRT1‐mediated NAMPT deacetylation, providing insights into sex differences in obesity‐associated OSA." (PMID 39901373, 2025). "Additionally, SIRT1, known for its role in mitochondrial biogenesis and adipogenesis, was identified as another key player, reinforcing its involvement in obesity progression and its reduced expression in the myocardium of diabetic patients, further emphasizing its connection to diabesity." (PMID 40697662, 2025). "Thus, the dysregulation of AMPK and SIRT1 signaling in obesity not only disrupts metabolic homeostasis but also contributes to associated neurobehavioral and hepatic complications, highlighting their potential as therapeutic targets for metabolic and psychiatric disorders." (PMID 41268687, 2025). "Genetic association studies have reported that single nucleotide variants (SNVs) in SIRT1, an NAD+-dependent deacetylase that plays an important role in the regulation of metabolic cellular functions, are associated with multiple metabolic disorders and the risk of obesity." (PMID 38645486, 2024). "Notably, in visceral AT, SIRT1 regulates adipogenesis, limiting obesity and glucose intolerance." (PMID 38255934, 2024). "Previous evidence suggests that Sirtuin 1 may act as a key gene in the prevention of obesity." (PMID 39403588, 2024). "We hypothesized that SIRT1 might influence the phenotype and functions of DCs through the Ido1 pathway, ultimately leading to the polarization towards pro-inflammatory T cells in obesity." (PMID 39424786, 2024). "Thus, alterations in SIRT1 levels during obesity could modulate DC phenotype towards an inflammatory profile as also shown here." (PMID 39424786, 2024). "This axis along with SIRT1 could benefit obesity-related CRC prognosis." (PMID 38704452, 2024). "To refine our findings, we generated a Sirt1 conditional knockout mouse strain (SIRT1∆) to specifically assess whether the absence of SIRT1 in dendritic cells affects the pro-inflammatory and metabolic profiles associated with obesity in vivo." (PMID 39424786, 2024). "Additionally, SIRT1 mediates the deacetylation of SIRT3 to mitigate obesity." (PMID 39355507, 2024). "Interestingly, SIRT1 is altered by obesity and unhealthy diets." (PMID 38026693, 2023). "Therefore, BDNF and sirtuin 1 may mediate the association between the MC4R rs17782313 polymorphism and obesity as well as hyperglycemia, which requires further investigation to confirm." (PMID 37621650, 2023). "Notably, quercetin showed to inhibit the obesity-associated inflammatory response via the adenosine monophosphate-activated protein kinase (AMPK) phosphorylation and the activation of sirtuin 1 (SIRT1) in macrophages, sharing the same mechanism of action as other flavonoids." (PMID 36769222, 2023). "Because SIRT-1 increases during weight loss and decreases in obese patients, the current findings may imply that SIRT-1 reduction plays a crucial role in MS disorders such as T2DM, IR, obesity, and NAFLD." (PMID 36991247, 2023).